U3 (Small nucleolar RNA U3 )
Synonyms: LOC124903436
Gene: Small nucleolar RNA gene on chromosome 14 (91,714,915 to 91,715,130, reverse strand). Ensembl gene ENSG00000275154.
Gene Ontology:
Biological process: RNA processing
Cellular component: nucleolus
Homologues: Orthologues: chimpanzee U3 (97% identical), macaque U3 (90% identical). Paralogues in human: SNORD3P1 (84% identical), U3 (81% identical), SNORD3E (81% identical), U3 (80% identical), U3 (79% identical), SNORD3D (78% identical), SNORD3H (77% identical), U3 (77% identical), SNORD3G (76% identical), U3 (76% identical), U3 (75% identical), U3 (74% identical), and 11 more.